PRTN3 (proteinase 3)
Diseases named in the same sentence as PRTN3 in open-access papers (continued):
Sharing a sentence is not in itself a finding about the gene and the disease.
osteoarthritis (3 papers, 2022 to 2024). A noninflammatory degenerative joint disease occurring chiefly in older persons, characterized by degeneration of the articular cartilage, hypertrophy of bone at the margins and changes in the synovial membrane. "PRTN3 is a member of the serine protease family, and its inhibition has shown promise in various contexts, such as in acute lung injuries, and antagonists of PAR2 have been investigated in relation to osteoarthritis." (PMID 38308214, 2024).
otitis media (3 papers, 2013 to 2020). Inflammation of the anatomical structures of the middle ear, which is most often caused by an infectious process. "Although myeloperoxidase and proteinase 3 anti-neutrophil cytoplasmic antibodies (MPO-ANCA, PR3-ANCA) were negative in the blood examination, otitis media with ANCA-associated vasculitis was suspected, and prednisolone (30 mg/day) was orally administered without antibiotics." (PMID 31918670, 2020).
pancreatic cancer (3 papers, 2020 to 2024). "Similar to our results, high PRTN3 expression also predicted poor prognosis in clear cell renal cell carcinoma and pancreatic cancer." (PMID 37231509, 2023). "High PRTN3 levels are also correlated with poor survival rates in pancreatic cancer." (PMID 33020388, 2020).
periodontal disease (3 papers, 2014 to 2022). "There are limited numbers of studies investigating the roles of proteinase 3 and cathepsin C in the pathogenesis of periodontal diseases." (PMID 24949444, 2014). "Further studies are needed to evaluate the activity of cathepsin C and proteinase 3 enzymes in different periodontal diseases as well as after periodontal treatment." (PMID 24949444, 2014). "The aim of the present study was to investigate gingival crevicular fluid (GCF) proteinase 3 and cathepsin C levels in periodontal diseases." (PMID 24949444, 2014). "The data of the present study might suggest a role for proteinase 3 during inflammatory immune responses in the pathogenesis of periodontal disease." (PMID 24949444, 2014). "In order to test this hypothesis, we aimed to determine the GCF levels of proteinase 3 and cathepsin C in patients with different periodontal diseases." (PMID 24949444, 2014). "Despite these limitations, a significant relationship between periodontal diseases and GCF levels of proteinase 3 was observed in the present study." (PMID 24949444, 2014).
Stroke (3 papers, 2016 to 2023). Sudden impairment of blood flow to a part of the brain due to occlusion or rupture of an artery to the brain. "Proteinase 3 (PR3) a neutrophil granule proteinase is elevated in the brain following stroke and is involved in the inflammatory process." (PMID 28443061, 2017). "In addition to neutrophil-derived MMPs, other factors released from neutrophils after stroke, including ROS, myeloperoxidase, elastase, cathepsin G, proteinase 3, cytokines, and chemokines, can also disrupt the neurovascular unit and ultimately result in increased BBB permeability and HT." (PMID 27561990, 2016).
acute respiratory distress syndrome (2 papers, 2020 to 2021). Progressive and life-threatening pulmonary distress in the absence of an underlying pulmonary condition, usually following major trauma or surgery. "Human neutrophil elastase (HNE) and proteinase 3 (Pr3) also represent potential oxime targets for the development of anti-inflammatory therapeutics to treat adult respiratory distress syndrome, autoimmune disorders, and hypersensitivity reactions." (PMID 34067242, 2021).
amyloid (2 papers, 2022 to 2023). "While higher PRTN3 may be protective, an interaction between immune genes, the amyloid-related LTF, and the tau-related ADAMTS2 could provide insights into how amyloid accelerates tau pathology." (PMID 35557837, 2022).
bladder cancer (2 papers, 2016 to 2023). "Urine IL-8, Ficolin-3, Apolipoprotein L1, Properdin, and Proteinase 3 also need to be validated both independently and as a multi-marker panel in future cross-sectional and longitudinal cohorts to confirm if they are good indicators for bladder cancer disease progression." (PMID 37016361, 2023).
cholangiocarcinoma (2 papers, 2014 to 2022). A carcinoma that arises from the intrahepatic biliary tree (intrahepatic cholangiocarcinoma) or from the junction, or adjacent to the junction, of the right and left hepatic ducts (hilar cholangiocarcinoma). "The involvement of autoimmunity in PSC has been further strengthened by recent data demonstrating that ANCAs to serine proteinase-3 (PR3-ANCAs) detected by bead-based immunoassays can occur in PSC and even have a predictive value for severe disease and the occurrence of cholangiocarcinoma (CCA)." (PMID 36359524, 2022).
co-infection (2 papers, 2021 to 2025). "In placental blood, indicators of neutrophil activation, myeloperoxidase (MPO) and proteinase 3 (PRTN3), are significantly elevated with PM and, more profoundly, with PM/HIV co-infection, in association with placental parasite density and hemozoin-bearing leukocyte accumulation." (PMID 34737733, 2021). "In placental blood collected from Kenyan women, MPO and proteinase 3 were substantially increased in instances of placental malaria and, more dramatically, in cases of placental malaria/HIV co-infection, correlating with placental parasite density and the accumulation of hemozoin-laden leukocytes." (PMID 40950582, 2025).
cognitive decline (2 papers, 2022 to 2024). "Tau load in the anterior cingulate and ADAMTS2, encoding a metallopeptidase, were the respective regional pathology and gene most associated with cognitive decline, while PRTN3, encoding a serine protease, was the key protective feature." (PMID 35557837, 2022). "We have shown that tau pathology in the ACC and two genes (PRTN3 and ADAMTS2) are strongly associated with the rate of cognitive decline in the ROSMAP cohort." (PMID 35557837, 2022). "Transcriptomic analysis suggested a role for several genes in cognitive decline with ADAMTS2 and PRTN3 featuring prominently, while tau pathology in the ACC was the most predictive neuropathological index from the ROSMAP neuropathology data." (PMID 35557837, 2022). "PRTN3 levels decreased, while ADAMTS2 increased with cognitive decline." (PMID 35557837, 2022). "ADAMTS2, but not PRTN3, was related to amyloid and tau load in the previous study while LTF was not related to cognitive decline here." (PMID 35557837, 2022).
gingivitis (2 papers, 2014 to 2020). A disorder involving inflammation of the gums; may affect surrounding and supporting structures of the teeth. "Elevated levels of GCF proteinase 3 in CP, G-AgP, and gingivitis might suggest that proteinase 3 plays a role during inflammatory periodontal events in host response." (PMID 24949444, 2014).
glioma (2 papers, 2020 to 2024). A benign or malignant brain and spinal cord tumor that arises from glial cells (astrocytes, oligodendrocytes, ependymal cells). "Interestingly, neutrophil serine proteases CTSG (Ctsg), NE (Elane) and PR3 (Prtn3) were among the SHs present in the ~ 25 kDa gel-pieces of glioma and bone marrow samples, in strong support for findings from tissue-ABPP." (PMID 32190011, 2020).
immune deficiency (2 papers, 2022 to 2025). "Serological level of immune biomarkers indicated immunodeficiency, and Proteinase 3-Anti-Neutrophil Cytoplasmic Antibody was positive." (PMID 36246283, 2022).
meningitis (2 papers, 2019 to 2022). A disorder characterized by acute inflammation of the meninges of the brain and/or spinal cord. "We used the following keywords: pachymeningitis, meningitis, dura, antineutrophil cytoplasmic antibody, myeloperoxidase, and proteinase-3." (PMID 36188377, 2022). "Shotgun proteomic analysis of the CSF from patients with meningitis confirmed the presence of NET-related proteins, such as MPO, NE, proteinase-3 (PR3), cathelicidin LL-37, MMP-9, heparin binding protein (HBP), neutrophil gelatinase-associated lipocalin (NGAL), and histones." (PMID 31766346, 2019).
overlap syndrome (2 papers, 2019 to 2023). "Also, if a patient with DM has proteinase 3 (PR3)-ANCA and paranasal sinusitis, can the patient be classified as having overlap syndrome consisting of DM and GPA ?" (PMID 37959218, 2023).
parasitemia (2 papers, 2021 to 2025). "Placental levels of MPO, MMP9, and PRTN3 all positively correlate with placental parasitemia as well as placental hemozoin bearing WBCs, suggesting that production is enhanced by chronic infection." (PMID 34737733, 2021).
peritonitis (2 papers, 2019 to 2022). Inflammation of the peritoneum (tissue that lines the abdominal wall and covers most of the organs in the abdomen). "In recent studies, the pro-inflammatory role of human proteinase 3 (PR3) during acute inflammatory responses by modulating neutrophil accumulation and the underlying mechanisms were almost entirely determined using a zymosan-induced peritonitis model." (PMID 31365522, 2019).
psoriasis (2 papers, 2016 to 2019). An autoimmune condition characterized by red, well-delineated plaques with silvery scales that are usually on the extensor surfaces and scalp. "Proteases released in the degranulation step by neutrophils, such as myeloperoxidase (MPO), neutrophil elastase (NE), proteinase 3, and cathepsin G, participate in the generation of ROS, proteolytical activation of inflammatory mediators, and formation of autoantigens in psoriasis." (PMID 31649677, 2019). "Proteinase 3 also contributes to the formation of the LL-37, an antimicrobial peptide belonging to cathelicidin family of polypeptides, which serves as autoantigen mediating immune response in psoriasis." (PMID 31649677, 2019). "Proteinase 3 cleaves and converts the resting TNFα located in membrane of epithelial cells (mTNFα) to an activated state called soluble TNFα (sTNFα), which participates in the psoriasis complex inflammatory reactions." (PMID 31649677, 2019). "Thus, the inhibition of neutrophils degranulation process or some of the enzymes contributing to psoriasis (NE, MPO, proteinase 3) are feasible targets for alleviating psoriatic symptoms." (PMID 31649677, 2019).
urinary tract infection (2 papers, 2019 to 2020). "Indeed the presence of PR3/PRTN3 or related neutrophil protease activities in normal urine is the basis for a dipstick based assay indicative of potential urinary tract infection." (PMID 32549867, 2020).
adenoma (1 paper, 2024). A neoplasm arising from the epithelium. "In this context, we highlight that AZU1 has also been previously observed as elevated in the stools of adenomas and CRC patients, as well as PRTN3, found in polyps and CRC tissues." (PMID 38612533, 2024).
allergic asthma (1 paper, 2019). A asthma with a basis in a pathological type I hypersensitivity reaction. "Greater DNAm of several CpGs annotated to the PRTN3 gene was associated with higher FeNO and allergic asthma." (PMID 31300640, 2019).
alpha 1-antitrypsin deficiency (1 paper, 2021). Alpha-1-antitrypsin deficiency is a hereditary disease that develops in adulthood and is characterized by chronic liver disorders (cirrhosis), respiratory disorders (emphysema), and rarely panniculitis. "In alpha-1-antitrypsin deficiency (AATD), neutrophil serine proteases such as elastase and proteinase 3 (PR3) are insufficiently inhibited." (PMID 34360796, 2021).
cerebral edema (1 paper, 2025). "Additionally, proteinase-3 (PR3, or PRTN3), which increases due to neutrophil degranulation in pediatric DKA, may degrade brain endothelial tight junctions, increasing the risk of cerebral edema." (PMID 39773407, 2025).
cerebral malaria (1 paper, 2024). A sequestration of Plasmodium falciparum in the brain, which can cause coma and/or seizures. "In falciparum malaria, retinopathy-positive cerebral malaria is specifically associated with vascular accumulation of externalized neutrophil proteins such as NE and proteinase-3." (PMID 39150978, 2024).
disseminated candidiasis (1 paper, 2018). Systemic candidiasis occurs when Candida yeast enters the bloodstream and may spread (becoming disseminated candidiasis) to other organs, including the central nervous system, kidneys, liver, bones, muscles, joints, spleen, or eyes. "For instance, host resistance to disseminated candidiasis is provided by neutrophil-derived proteinase 3 activation of IL-1β and not caspase-1 activation." (PMID 30583612, 2018).
E. coli infection (1 paper, 2022). "We demonstrate that IL-17A mediates TJs and AJs breakdown, thereby augmenting BBB permeability via inhibiting PRTN3/PAR2 axis during meningitic E. coli infection, leading to severe neuroinflammation and neuronal injury." (PMID 35221923, 2022).
Fever (1 paper, 2021). Body temperature elevated above the normal range. "Importantly, MPO, MMP9 and PRTN3 levels in the placenta associate with self-reported fever in this cohort of parturient women." (PMID 34737733, 2021).
gastric cancer (1 paper, 2024). A primary or metastatic malignant neoplasm involving the stomach. "In our analysis of various cancer types in the TCGA database, we found that the PRTN3-expressing group with gastric cancer had decreased overall survival." (PMID 38308214, 2024).
Graves disease (1 paper, 2021). Graves' disease is an autoimmune disorder that leads to overactivity of the thyroid gland (hyperthyroidism).It is caused by an abnormal immune system response that causes the thyroid gland to produce too much thyroid hormones. "Blood test results showed elevated levels of myeloperoxidase (MPO)-ANCA and proteinase 3 (PR3)-ANCA, which were negative before the patient had received treatment for Graves’ disease, suggesting the presence of propylthiouracil-induced AAV." (PMID 34451967, 2021). "Her serum myeloperoxidase-ANCA and proteinase 3-ANCA levels, which were negative before the Graves’ disease treatment, were elevated." (PMID 34451967, 2021).
hemorrhage (1 paper, 2022). Loss of blood from the vascular compartment to the exterior or into nonvascular body space as a result of rupture or severance of the blood vessels. "Interestingly, two proteins (uPA and PRTN3) in the CB group and three proteins (vWF, uPA, and EPHB4) in the RB group were also the significant proteins selected by LASSO logistic regression and random forest, among which only PRTN3 was related to hemorrhage and coagulation in the RF group." (PMID 36704472, 2022).
hyperhomocysteinemia (1 paper, 2023). A serious metabolic condition caused by mutations in the MTHFR gene, medications, or nutritional deficiency. "Here, we report a case of CVST and Hyperhomocysteinemia in Proteinase 3 anti-neutrophil cytoplasmic antibody (PR3-ANCA) positive GPA without renal involvement." (PMID 37273400, 2023).
Interstitial pneumonitis (1 paper, 2014). "In addition, membrane-bound proteinases, such as proteinase 3 that is involved in activation and inactivation modes of PAR-2, was also expressed in neutrophils and alveolar macrophages clearing TNF-α, which is more common in interstitial pneumonitis than in SARC." (PMID 25009615, 2014).
lung adenocarcinoma (1 paper, 2025). A carcinoma that arises from the lung and is characterized by the presence of malignant glandular epithelial cells. "Immunohistochemistry was used to detect the level of PRTN3 in lung adenocarcinoma (LUAD) tissue array." (PMID 40028338, 2025).
lymph node metastasis (1 paper, 2022). "Second, given that it is difficult to establish the presence of lymph node metastasis in many patients, the effect of the expression of AIM2, DFNB59, NLRP11 and PRTN3 on T staging was not fully investigated." (PMID 35281845, 2022).
meningioma (1 paper, 2020). A generally slow growing tumor attached to the dura mater. "Proteins involved in neutrophil degranulation, such as ARSA, GCA, FUCA1, PRTN3, ELANE, MNDA, and LCN2, were identified uniquely or with differential abundance in male meningiomas." (PMID 32587372, 2020).
mitral valve insufficiency (1 paper, 2025). A mitral valve disorder characterized by incomplete valve closure. "We present the case of a 59-year-old woman with known anti-proteinase 3 (PR3)-ANCA-positive GPA who developed a severe disease flare characterized by diffuse alveolar hemorrhage (DAH) and mitral valve insufficiency due to chordae tendineae rupture." (PMID 40786364, 2025).
mucositis (1 paper, 2020). Mucositis is inflammation and damage of the mucous membranes lining the mouth and other parts of the gastrointestinal (GI) tract. "Since the purpose of this current study was to evaluate PISF proteinase 3 and LL-37 levels in the presence of peri-implant tissue destruction, implants with peri-implant mucositis were also included in the control group." (PMID 32748292, 2020).
Neonatal sepsis (1 paper, 2021). Systemic inflammatory response to infection in newborn babies. "Hence, the lower methylation levels observed in the promoters of genes involved in neutrophil activation (i.e., ATP8B4, LRG1, TREM1, PRTN3, S100A8, ELANE, and CD177) illustrates the role of DNAm in innate immunity in neonatal sepsis." (PMID 33659006, 2021).
osteomyelitis (1 paper, 2025). An acute or chronic inflammation of the bone and its structures due to infection with pyogenic bacteria. "Additionally, current literature suggests that a sustained inflammatory response involving MPO and PRTN3 may contribute to the transition from acute to chronic osteomyelitis." (PMID 41278027, 2025). "Further experiments could be conducted to explore the mechanisms of chronic osteomyelitis formation by regulating MPO and PRTN3." (PMID 41278027, 2025).
Peri-Implantitis (1 paper, 2020). An inflammatory process with loss of supporting bone in the tissues surrounding functioning DENTAL IMPLANTS. "Therefore, in this study, the hypothesis is that peri-implant tissue destruction caused by peri-implantitis might affect the LL-37 and proteinase 3 amounts in peri-implant sulcus fluid (PISF)." (PMID 32748292, 2020). "Therefore, studies investigating PISF proteinase 3 levels in peri-implant healthy, peri-implant mucositis, and peri-implantitis might yield more information regarding the pathogenesis of peri-implant diseases." (PMID 32748292, 2020). "Our findings demonstrated no important changes in PISF LL-37 and proteinase 3 total amounts between implants with and without peri-implantitis." (PMID 32748292, 2020). "In this current study, proteinase 3 levels in PISF were similar between peri-implantitis and non-peri-implantitis sites." (PMID 32748292, 2020). "However, peri-implant tissue destruction caused by peri-implantitis does not seem to affect PISF LL-37 and proteinase 3 levels." (PMID 32748292, 2020). "Accordingly, the aim is to evaluate LL-37 and proteinase 3 amounts in PISF in implant sites with and sites without peri-implantitis, in order to detect temporal changes regarding the progression of the disease." (PMID 32748292, 2020). "In the present study, the aim was to evaluate LL-37 and proteinase 3 levels in peri-implant sulcus fluid (PISF) in implants with and without peri-implantitis." (PMID 32748292, 2020).
pneumococcal meningitis (1 paper, 2023). An acute purulent infection of the meninges and subarachnoid space caused by Streptococcus pneumoniae, most prevalent in children and adults over the age of 60. "Analysis of cerebrospinal fluid (CSF) from humans and rodents with pneumococcal meningitis reveals the presence of neutrophils and externalized neutrophil proteins such as myeloperoxidase (MPO), histones, NE, and proteinase 3 (PR3), which may imply NET production." (PMID 36873885, 2023).
pustular psoriasis (1 paper, 2023). "Other genes involved in pustular psoriasis are SERPINA1 and SERPINA3 (serine protease inhibitors that inhibit cathepsin G, neutrophil elastase, and proteinase 3), TNIP1 and IL1RN." (PMID 37628670, 2023).